GOSR1 (golgi SNAP receptor complex member 1)
Description:
Involved in transport from the ER to the Golgi apparatus as well as in intra-Golgi transport. It belongs to a super-family of proteins called t-SNAREs or soluble NSF (N-ethylmaleimide-sensitive factor) attachment protein receptor. May play a protective role against hydrogen peroxide induced cytotoxicity under glutathione depleted conditions in neuronal cells by regulating the intracellular ROS levels via inhibition of p38 MAPK (MAPK11, MAPK12, MAPK13 and MAPK14). Participates in docking and fusion stage of ER to cis-Golgi transport. Plays an important physiological role in VLDL-transport vesicle-Golgi fusion and thus in VLDL delivery to the hepatic cis-Golgi.
Synonyms: GOS-28; GS28; GOS28; P28; GOLIM2; GOS28/P28
Tractability: Antibody: UniProt predicts a signal peptide or a membrane-spanning region. PROTAC: ubiquitination databases record sites on it; its protein half-life has been measured.
Gene: Protein-coding gene on chromosome 17 (30,477,362 to 30,527,592, forward strand). Ensembl gene ENSG00000108587.
Subcellular location: Golgi apparatus membrane
Pathways (Reactome):
Vesicle-mediated transport: COPI-mediated anterograde transport; Intra-Golgi traffic
Gene Ontology:
Molecular function: SNAP receptor activity
Biological process: retrograde transport, endosome to Golgi; endoplasmic reticulum to Golgi vesicle-mediated transport; inter-Golgi cisterna vesicle-mediated transport; intra-Golgi vesicle-mediated transport; vesicle fusion
Cellular component: Golgi apparatus; Golgi membrane; membrane; Golgi medial cisterna; SNARE complex; transport vesicle; cis-Golgi network; cytosol
Genetic constraint (gnomAD): Loss-of-function variants: 1 observed, 1.96 expected, observed/expected ratio (o/e) 0.51, 90% interval 0.17 to 1.75. That is too few expected variants to judge how well the gene tolerates losing a copy. Missense variants: 14 observed, 9.57 expected, observed/expected ratio (o/e) 1.46, 90% interval 0.94 to 1.92. Synonymous variants: 4 observed, 2.42 expected, observed/expected ratio (o/e) 1.65, 90% interval 0.68 to 1.94.
Homologues: Orthologues: chimpanzee GOSR1 (99% identical), pig GOSR1 (98% identical), guinea pig GOSR1 (98% identical), mouse Gosr1 (98% identical), rat Gosr1 (96% identical), tropical clawed frog gosr1 (90% identical), zebrafish gosr1 (88% identical), dog GOSR1 (74% identical), macaque GOSR1 (72% identical), rabbit GOSR1 (71% identical), Drosophila melanogaster Gos28 (46% identical), Caenorhabditis elegans gos-28 (35% identical).
Diseases named in the same sentence as GOSR1 in open-access papers:
GOSR1 is named in the same sentence as 12 diseases in open-access papers, as found by Europe PMC text mining. Sharing a sentence is not in itself a finding about the gene and the disease. The quoted sentences say what the papers report.
esophageal SCC (2 papers, 2011 to 2022). "The GOSR1 protein is responsible for cellular trafficking and is frequently upregulated in esophageal squamous cell carcinoma tissues." (PMID 35893234, 2022). "Reverse transcription followed by quantitative PCR analysis showed that the mRNA expression levels of ECSA-1, -2 and -3 and FAM119A but not of HCA25a, GOSR1 and BBS5 were frequently elevated in esophageal SCC tissues." (PMID 21696638, 2011).
glioma (1 paper, 2020). A benign or malignant brain and spinal cord tumor that arises from glial cells (astrocytes, oligodendrocytes, ependymal cells). "We chose the three genes most significantly enriched in the high-EGFR gliomas: GOSR1, TMEM167A, and STX17." (PMID 31947645, 2020).
lung carcinoma (1 paper, 2021). "Similar NF1/GOSR1 gene rearrangements causing inactivation of the NF1 gene have also been reported in lung cancer, where they are thought to play a role in the onset of adenocarcinomas lacking known driver mutations." (PMID 34944796, 2021).
tumor (2 papers, 2011 to 2016). "On the other hand, the expression levels of HCA25a and GOSR1 were relatively low and not apparently different between the tumor and normal tissues." (PMID 21696638, 2011).
GOSR1 also shares sentences with these, for which no sentence is quoted: cancer (2 papers); adenocarcinoma (1); cervical cancer (1); cervical tumor (1); colorectal cancer (1); lymph node metastasis (1); neurological disorders (1); sarcoma (1).